TSSK2 (testis specific serine kinase 2)
Description:
Testis-specific serine/threonine-protein kinase required during spermatid development. Phosphorylates TSKS at 'Ser-288' and SPAG16. Involved in the late stages of spermatogenesis, during the reconstruction of the cytoplasm. During spermatogenesis, required for the transformation of a ring-shaped structure around the base of the flagellum originating from the chromatoid body.
Synonyms: TSK2; DGS-G; SPOGA2; STK22B; FLJ38613
Tractability: Small molecule: a high-quality ligand is known; it belongs to a druggable protein family. PROTAC: UniProt records ubiquitination sites on it; a small molecule that binds it is known.
Target class: CAMK protein kinase TSSK family; CAMK protein kinase group; Protein Kinase; Enzyme; Kinase
Gene: Protein-coding gene on chromosome 22 (19,131,308 to 19,132,622, forward strand). Ensembl gene ENSG00000206203.
Subcellular location: Cytoplasm; Cytoplasm, cytoskeleton, microtubule organizing center, centrosome, centriole
Gene Ontology:
Molecular function: magnesium ion binding; protein binding; protein serine kinase activity; protein serine/threonine kinase activity; ATP binding; protein kinase activity; protein-containing complex binding
Biological process: protein autophosphorylation; spermatid development
Cellular component: nucleus; cytoplasm; acrosomal vesicle; centriole
Genetic constraint (gnomAD): Loss-of-function variants: 10 observed, 21.05 expected, observed/expected ratio (o/e) 0.48, 90% interval 0.29 to 0.81. The upper end of that interval is the gene's LOEUF score, 0.81, which puts it in group 3 of 6, group 1 being the genes least tolerant of losing a copy. Missense variants: 439 observed, 513.97 expected, observed/expected ratio (o/e) 0.85, 90% interval 0.79 to 0.92. Synonymous variants: 209 observed, 210.89 expected, observed/expected ratio (o/e) 0.99, 90% interval 0.88 to 1.11.
Homologues: Orthologues: chimpanzee TSSK2 (99% identical), macaque TSSK2 (97% identical), dog TSSK2 (94% identical), pig TSSK2 (94% identical), mouse Tssk2 (92% identical), rat Tssk1b (92% identical), rabbit TSSK2 (91% identical), guinea pig Tssk2 (87% identical), Drosophila melanogaster Snrk (32% identical), Caenorhabditis elegans C27D6.11 (30% identical), Caenorhabditis elegans tag-344 (30% identical), Caenorhabditis elegans Y38H8A.4 (30% identical), and 1 more. Paralogues in human: TSSK1B (68% identical), SIK1 (36% identical), TSSK3 (35% identical), NUAK2 (35% identical), TSSK4 (35% identical), TSSK6 (35% identical), NUAK1 (34% identical), SIK3 (34% identical), SIK2 (33% identical), HUNK (32% identical), SNRK (32% identical), PRKAA2 (31% identical), and 5 more.
Diseases named in the same sentence as TSSK2 in open-access papers:
TSSK2 is named in the same sentence as 8 diseases in open-access papers, as found by Europe PMC text mining. Sharing a sentence is not in itself a finding about the gene and the disease. The quoted sentences say what the papers report.
male infertility (8 papers, 2018 to 2025). The inability of the male to effect fertilization of an ovum after a specified period of unprotected intercourse. "Furthermore, when men with azoospermia or severe oligozoospermia were compared to fertile controls, single nucleotide polymorphisms in the TSSK2 gene were associated with idiopathic male infertility." (PMID 36875503, 2023). "TSSK2 gene may play an indispensable role in spermatogenesis process, and is associated with male idiopathic infertility in humans." (PMID 36181097, 2022). "Knockout (KO) mouse models have shown that Tssk1 and Tssk2 play roles in male infertility, affecting testis development and/or fertilization." (PMID 38245531, 2024). "Remarkably, the transcripts encoding genes such as ZMYND15, KLHL10, TDRD1, TSSK2 and DNAJB13, which are linked to male infertility in other species, were differentially expressed among the treatments." (PMID 30697164, 2018). "Targeted deletion of Tssk1 and Tssk2 results in disruption of spermiogenesis and male infertility." (PMID 41155324, 2025). "Insufficient expression of TSSK2 could interrupt spermiogenesis and results in failure of elongated spermatids, triggering male infertility." (PMID 30697164, 2018).
Azoospermia (2 papers, 2023). Absence of any measurable level of sperm,whereby spermatozoa cannot be observed even after centrifugation of the semen pellet. "Indeed, single-nucleotide mutations of TSSK2, TSSK4, and TSSK6 are reportedly associated with azoospermia and severe oligospermia." (PMID 37149634, 2023).
DiGeorge Syndrome (2 papers, 2022 to 2025). "In humans, TSSK1A gene is located in tandem with TSSK2 within the DiGeorge Syndrome region on chromosome22q11.2195." (PMID 35173218, 2022). "In humans, TSSK2 is found in the DiGeorge syndrome minimal region in chromosome 22." (PMID 40305308, 2025).
oligospermia (1 paper, 2017). Decreased number of spermatozoa in the semen. "Three down-regulated genes (PLCZ1, TSSK2 and ANKRD7) were common between MArrest, oligospermia and the Dazap1 mouse mutant." (PMID 29150651, 2017).
cancer (2 papers, 2020 to 2023). A tumor composed of atypical neoplastic, often pleomorphic cells that invade other tissues. "In this context, three separate laboratories have reported TSSK2, TSSK3, and TSSK6 in different cancer types." (PMID 32337545, 2020). "In addition, members of the TSSK family such as TSSK2, TSSK3, and TSSK6 play important roles in survival and proliferation of cancer cells, and TSSK6 is an immunogenic cancer/testis antigen in various cancers." (PMID 37149634, 2023).
TSSK2 also shares sentences with these, for which no sentence is quoted: systemic sclerosis (2 papers); Infertility (1); tumor (1).